CTNNB1 (catenin beta 1)
Diseases named in the same sentence as CTNNB1 in open-access papers (continued):
Sharing a sentence is not in itself a finding about the gene and the disease.
melanoma (89 papers, 2008 to 2026). A malignant, usually aggressive tumor composed of atypical, neoplastic melanocytes. "Wnt GOF was achieved using the Ctnnb1Ex3-lox allele, which allows Ctnnb1 exon 3 depletion and subsequent Ctnnb1 stabilization upon Cre recombination and promotes melanoma initiation in the same oncogenic setting." (PMID 41063628, 2025). "ARF6 is a GTPase that regulates N-Cadherin-associated CTNNB1, resulting in its sequestration or liberation and subsequent relocation to the nucleus in melanoma cells." (PMID 38854152, 2024). "Activating mutations in CTNNB1, especially in exon 3, were detected in many cancers, including melanoma." (PMID 39340537, 2024). "A recent review summarizing data from multiple next generation sequencing (NGS) approaches found only eight CTNNB1 mutations in 686 melanomas (1.2%)." (PMID 36077603, 2022). "The study’s significant findings are that APC/CTNNB1 somatic mutations have adverse prognosis in later stages of melanoma." (PMID 34986841, 2022). "To assess the role of CTNNB1 mutations in advanced melanoma, we screened our large genetic melanoma database identifying 38 tumors—to our knowledge the largest cohort of CTNNB1-mutated advanced melanoma reported to date." (PMID 36077603, 2022). "We found that mutations in the beta-catenin gene CTNNB1 had the highest contribution for prediction, in agreement with recent findings that activation of this gene in melanoma cells is associated with a reduction in T-cell antitumor response." (PMID 36123351, 2022). "Little is known about the association between the adenomatous polyposis coli (APC) and CTNNB1 gene mutations in stage IV melanoma with immunotherapy response and overall survival (OS)." (PMID 34986841, 2022). "Larger studies, optimally in a prospective fashion will be required to further elucidate if CTNNB1 mutation status should be clearly linked to specific systemic therapy recommendations in advanced melanoma patients." (PMID 36077603, 2022). "Another large retrospective study including NGS data from 467 melanoma patients identified ten primary melanoma patients harboring a CTNNB1 mutation." (PMID 36077603, 2022). "In this study, CTNNB1 mutations only occurred in BRAF or NRAS mutated melanomas, suggesting a cooperation between MAPK and Wnt/β-catenin signaling pathways." (PMID 36077603, 2022). "Data acquired from routinely performed NGS panel analysis of histopathologically clearly diagnosed melanomas analyzed between 2014 and 2021 were assessed to identify samples harboring CTNNB1 mutations." (PMID 36077603, 2022). "We assessed APC/CTNNB1 mutations as predictors of response to immunotherapies in a clinicopathologically annotated metastatic patient cohort from three US melanoma centers." (PMID 34986841, 2022). "Here, we provide the current knowledge of this pathway in melanoma, especially through the activity of β-catenin, which is encoded by CTNNB1." (PMID 35158973, 2022). "We identified CTNNB1 mutations in two types of melanocytic tumors, benign nevi and malignant melanoma." (PMID 36077603, 2022). "Seven cases with CTNNB1 mutations were identified, two classified as malignant, one as a “deep blue nevus-like melanoma” (case 3) and a “malignant melanoma morphologically resembling a deep penetrating blue nevus” (case 6)." (PMID 36077603, 2022). "Significant changes on the transcriptomic level of genes involved in the Wnt/β-catenin signaling pathway underline a biological regulation of this pathway in CTNNB1-mutant melanoma." (PMID 36077603, 2022). "In total, 38 mutations in melanoma from 38 patients in the exon 3 hotspot of CTNNB1 were identified." (PMID 36077603, 2022).
melanoma (continued). "Mutations in the CTNNB1 gene are rare: around 3% in melanoma except for the deep penetrating nevus (DPN) that harbors 90% of activating mutations in CTNNB1." (PMID 35158973, 2022). "In melanoma, mutations in CTNNB1 (typically missense mutations localized in exon 3) are relatively infrequent (around 7%)." (PMID 32850962, 2020). "An early study reported mutations in CTNNB1 in six of 26 melanoma cell lines, and all these mutations affect phosphorylation of β-catenin rending it resistant to proteasomal degradation." (PMID 32659938, 2020). "The remaining 22 lung cancers and all 10 CTNNB1 mutated melanomas were scored as monoallelic/heterozygous." (PMID 33115416, 2020). "For example, only 1 of 65 primary melanomas harbored mutations of CTNNB1, and one third of cases showed nuclear accumulation of β-catenin." (PMID 32659938, 2020). "CTNNB1 mRNA profile alteration, which encodes β-catenin protein, was found in melanoma, breast colorectal, lung, prostate, and other cancers." (PMID 31462944, 2019). "Also in melanoma it was shown that T cell depleted tumours often have an activating CTNNB1 mutation." (PMID 40130164, 2025). "In ClinVar database, CTNNB1 p.(Ser37Phe) is reported as a “Pathogenic/Likely pathogenic” variant in multiple tumor types (e.g., prostate, hepatocellular, gastric, ovary, and melanoma) and as a somatic oncogenic event in pilomatrixoma (Variation ID: 17586; last accessed on 1 February 2023)." (PMID 40843798, 2025). "In addition, the role of CTNNB1 mutations in a large cohort of advanced melanoma was analyzed to study potential associations with clinical characteristics, outcome and therapy responses." (PMID 36077603, 2022). "Interestingly, we found that different subsets of CIBERSORT-inferred T cells are significantly higher in CTNNB1 mutated melanoma tumors compared to wild-type CTNNB1 tumors." (PMID 36123351, 2022). "Activating mutations of CTNNB1 have been reported in a range of cancers including melanoma." (PMID 36077603, 2022). "For patients with advanced melanoma in whom CTNNB1 mutations are unexpectedly discovered during routine molecular profiling, the extent to which they might impact patient therapy may be the most important question to consider." (PMID 36077603, 2022). "We thus conclude that although APC/CTNNB1 mutations may contribute to the development of parenchymal brain metastases, melanoma-intrinsic β-catenin signaling plays a less significant role." (PMID 34986841, 2022). "Noteworthy was also the observation from the 3-institution cohort that genetic aberrations of specific melanoma-associated genes were less frequent in APC/CTNNB1-mutant stage IV melanomas than the incidence of these mutations without (e.g., NF1, RAC1, and PTEN)." (PMID 34986841, 2022). "Studies with larger numbers of difficult to classify melanocytic lesions as well as CTNNB1 mutated melanomas may offer further insights." (PMID 36077603, 2022). "To further evaluate the role of CTNNB1 mutations in melanoma, we assessed a large cohort of clinically sequenced melanomas, identifying 38 tumors with CTNNB1 exon 3 mutations, including recurrent S45 (n = 13, 34%), G34 (n = 5, 13%), and S27 (n = 5, 13%) mutations." (PMID 36077603, 2022). "Recurrent CTNNB1 exon 3 mutations have been recognized in the distinct group of melanocytic tumors showing deep penetrating nevus-like morphology and in 1–2% of advanced melanoma." (PMID 36077603, 2022). "Performing a detailed genetic analysis of difficult-to-classify nevi and melanomas with CTNNB1 mutations, we found that benign tumors (nevi) show characteristic morphological, genetic and epigenetic traits, which distinguish them from other nevi and melanoma." (PMID 36077603, 2022). "Melanoma was one of the first cancers in which CTNNB1 mutations were identified." (PMID 35158973, 2022).
melanoma (continued). "We performed a detailed genetic analysis of difficult-to-classify nevi and melanomas with CTNNB1 mutations and found that benign tumors (nevi) show characteristic morphological, genetic and epigenetic traits, which distinguish them from other nevi and melanoma." (PMID 36077603, 2022). "β-catenin hyperactivation in melanoma is rarely caused by mutations of CTNNB1." (PMID 32659938, 2020). "The Wnt pathway may be altered in melanomas by different mechanisms, e.g., somatic variants not only in CTNNB1 but also in APC (adenomatous polyposis coli gene) or ICAT (inhibitor of beta-catenin) genes." (PMID 32850962, 2020). "We report here development, validation, and implementation of an assay designed to simultaneously detect 43 common somatic point mutations in 6 genes (BRAF, NRAS, KIT, GNAQ, GNA11, and CTNNB1) potentially relevant to existing and emerging targeted therapies specifically in melanoma." (PMID 22536370, 2012). "This mutation has not been reported in COSMIC or TCGA (accessed April 18, 2019), and we previously identified heterogeneous CTNNB1 mutations in multiple metastases following a single primary melanoma, indicating that melanomas may harbor passenger CTNNB1 mutations." (PMID 31811783, 2020). "Although mutations in CTNNB1 are rare in melanomas, activation might be through upstream modulators because a survey of large collection of melanoma tumors in tissue microarrays demonstrated that activated β-catenin in the nucleus is an independent predictor of poor survival." (PMID 19234609, 2009). "In melanoma cell lines as well as dendritic cells (DC), experimental overexpression of CTNNB1 has been shown to increase interleukin (IL) IL-10 secretion and to impede the ability of DCs to cross-prime tumour-targeting CD8+ T cells." (PMID 40130164, 2025). "Mechanistically, YTHDF3 has been found to facilitate the translation of Catenin Beta 1 (CTNNB1), a driver gene implicated in melanoma genesis, via an m6A-dependent mechanism." (PMID 39342406, 2024). "CTNNB1 activation, through the Wnt/β-Catenin pathway, subsequently contributes to melanoma progression and metastasis." (PMID 39342406, 2024). "In melanoma, TERT promoter mutations, MITF, and CTNNB1 were amongst the genes enriched in metastatic vs. primary Class 1 BRAF mutant tumors." (PMID 38275886, 2024). "The median OS of patients with APC/CTNNB1-mutant melanomas trended to be significantly shorter compared to melanomas without APC/CTNNB1 mutations (29 vs. 36.3 months, log-rank HR 1.57, 95CI 0.92–2.69, p = 0.099)." (PMID 34986841, 2022). "Malignant CTNNB1-mutant tumors (melanoma) demonstrated a different genetic profile, grouping clearly with other non-CTNNB1 melanomas in methylation assays." (PMID 36077603, 2022). "Several genes have been identified as genetically altered drivers of melanoma tumorigenesis, such as NRAS, CDNK2A, MITF, PTEN, KIT, GNAQ, GNA11 or CTNNB1, but most (60%) melanomas have BRAF gene mutations." (PMID 35326682, 2022). "The second cohort only included patients with stage IV melanoma who were predominantly (> 85%) treated with PD1 inhibitors across three US melanoma institutions and was enriched for patients with APC/CTNNB1 mutations (25%, retrospective chart review analysis)." (PMID 34986841, 2022). "A biphenotypic epithelioid and plexiform melanoma with DPN-like features was shown to demonstrate BRAF and PTEN mutations in both components but a CTNNB1 mutation only in the DPN-like areas." (PMID 35336833, 2022). "This study investigated the clinical (i.e., theragnostic) significance of APC/CTNNB1 genetic aberrations across two clinicopathologically annotated melanoma patient cohorts." (PMID 34986841, 2022).
melanoma (continued). "In this study, we investigated the clinical significance, prognostic and predictive, of APC and CTNNB1 genetic aberrations in melanoma patients." (PMID 34986841, 2022). "Nevertheless, each patient cohort had its limitations in data interpretation and generalizability of findings, in part related to the low incidence of APC/CTNNB1 genetic aberrations in melanoma." (PMID 34986841, 2022). "Malignant CTNNB1-mutant tumors (melanomas) demonstrated a different genetic profile, instead grouping clearly with other non-CTNNB1 melanomas in methylation assays." (PMID 36077603, 2022). "Therapy response to anti-PD1 monotherapy showed an overall response rate (ORR) of 67% (6/9 patients) in patients with CTNNB1-mutant melanoma compared to 36% (49/135 patients) in those with CTNNB1-wild type tumors." (PMID 36077603, 2022). "The median OS of patients with APC/CTNNB1-mutant melanomas was significantly shorter than that of patients bearing wild-type APC/CTNNB1 melanomas (8.15 vs. 22.8 months, log-rank HR 4.2, 95CI 1.38–12.58, p = 0.011)." (PMID 34986841, 2022). "Methylation analysis was performed on the seven described CTNNB1-mutant tumors and the profiles were compared to control groups consisting of eight benign nevi, eight malignant melanomas and five Spitz nevi." (PMID 36077603, 2022). "Although CTNNB1 has been reported to induce melanoma metastasis, it has also been described to limit invasion of melanoma in an experimental setting in both human and mice." (PMID 36077603, 2022). "Based on our and existing data to date, we believe no clear-cut recommendation concerning therapeutic approach or prognosis concerning survival can be made for CTNNB1-mutant melanoma." (PMID 36077603, 2022). "CTNNB1-mutant melanomas were found to originate from different locations and only rarely demonstrated a deep penetrating phenotype." (PMID 36077603, 2022). "Nonsynonymous SNVs in the CDK4, MUM1 and CTNNB1 genes were among the first neoantigens isolated from melanoma by this approach." (PMID 34885172, 2021). "In melanoma, frequencies of mutations in APC, AXIN1 and CTNNB1 are low, reaching according to cbioportal.org 10%, 2.9% and 5.9%, respectively, however, a significant interstudy variability exists." (PMID 32659938, 2020). "One report described a melanoma with GOLGA4 fused to exons 8–17 of RAF1, retaining the RAF1 kinase domains, and with accompanying mutations in CTNNB1 and CDKN2A." (PMID 32123303, 2020). "The authors also identified that malignant DPN (melanomas arising in DPN) demonstrated additional genetic alterations (to MAP kinase activating and CTNNB1 mutations)." (PMID 32509588, 2020). "Several later studies have shown much lower frequencies of mutations in CTNNB1 and APC, which put into question the importance of a genetic component in aberrant activity of β-catenin in melanoma." (PMID 32659938, 2020). "In contrast, Ctnnb1 (beta-catenin), Egfr and Pten mutations are associated with decreased CD8+ T cell infiltration in melanoma, non-small cell lung carcinoma and prostate cancer, respectively." (PMID 29883385, 2018). "In keeping with published studies, there were frequent mutations of BRAF and NRAS in melanoma; BRAF, EGFR, KRAS, and STK11 in NSCLC; APC, BRAF, KRAS, and PIK3CA in CRC; KIT and PDGFR3A in GIST; and CTNNB1 in other tumours (desmoid fibromatosis)." (PMID 28196074, 2017). "We therefore examined the effects of transient knockdown of β-catenin in PTENWT WNT3A overexpression melanoma cells using small interfering RNA (siRNA) and found efficient reduction of CTNNB1 gene expression in response to treatment." (PMID 28092677, 2017). "Melanoma cell populations also differed in the expression of β-catenin with a substantially higher level of CTNNB1 transcript in DMBC21 and DMBC17 populations than DMBC12, DMBC11 and DMBC19 populations." (PMID 27351373, 2016).
melanoma (continued). "To identify miR-514a regulated targets we conducted a miR-514a-mRNA ‘pull-down’ experiment, which revealed hundreds of genes, including: CTNNB1, CDK2, MC1R, and NF1, previously associated with melanoma." (PMID 25980496, 2015). "PLX4720 increased Wnt signaling and induced Bim expression and cell death in A375 melanoma cells, which was blocked by β-catenin (CTNNB1) siRNA." (PMID 24809668, 2014). "Directing this test to a single disease, 90 of 150 (60%) melanomas from sites throughout the body harbored a mutation tested, including 57, 23, 6, 3, and 2 mutations in BRAF, NRAS, GNAQ, KIT, and CTNNB1, respectively." (PMID 22536370, 2012). "Similarly, miR‐214 targets CTNNB1, a critical component of the Wnt pathway, and downregulation of CTNNB1 by miR‐214 reduces cell invasiveness and metastatic potential in melanoma." (PMID 39823244, 2025). "We found that APC and CTNNB1 somatic mutations do not significantly coexist with somatic mutations in other melanoma-associated genes after controlling for somatic tumor mutation burden." (PMID 34986841, 2022). "APC/CTNNB1 mutations are associated with a worse outcome in stage IV melanoma and early brain metastases independent of tumor-infiltrating lymphocyte density." (PMID 34986841, 2022). "Mutation co-occurrence analysis showed that no somatic mutations in other melanoma-associated genes were significantly correlated with APC/CTNNB1 somatic mutations after controlling for tumor mutation burden and multiple testing comparisons (data not shown)." (PMID 34986841, 2022). "When the data from the 82 patients with stage IV melanoma were fitted into a Cox proportional hazard model that included the APC/CTNNB1 mutation status and the mutation burden as covariates, the APC/CTNNB1 mutation status coefficient remained significant (p = 0.0245)." (PMID 34986841, 2022). "The two malignant CTNNB1-mutant tumors (ID 3 + 6) clustered towards the melanoma group." (PMID 36077603, 2022). "In the TCGA-SKCM patient cohort (n = 434) presence of a somatic APC/CTNNB1 mutation was associated with a worse outcome only in stage IV melanoma (n = 82, median OS of APC/CTNNB1 mutants vs. wild-type was 8.15 vs. 22.8 months; log-rank hazard ratio 4.20, p = 0.011)." (PMID 34986841, 2022). "Analysis of the prognostic significance of somatic APC/CTNNB1 mutations from the entire TCGA SKCM cohort provided a direct comparison between melanoma patients with or without APC/CTNNB1 somatic mutations." (PMID 34986841, 2022). "Comparison of transcriptomic expression (measured in transcripts per million [TPM]) of multiple genes involved in this Hallmark WNT β-catenin signaling pathway showed significant differences in the expression of CTNNB1-mutant and CTNNB1-wild type melanoma patients." (PMID 36077603, 2022). "We believe the following reasons may explain the discrepancy between our findings regarding clinical benefit from immunotherapies in patients with APC/CTNNB1-mutant melanoma and previous preclinical or translational observations." (PMID 34986841, 2022). "In contrast with preclinical data suggesting that activation of the β-catenin pathway in melanoma cells associates with resistance to anti-PD-L1/anti-CTLA-4 antibody therapy, we found that more than 50% of patients with APC/CTNNB1 genetic aberrations responded to immunotherapies." (PMID 34986841, 2022). "Locations and histological subtype of CTNNB1-mutated melanoma varied; none were reported as showing deep penetrating nevus-like morphology." (PMID 36077603, 2022). "Median number of total mutations, nonsynonymous mutations, clonal and subclonal mutations were higher in CTNNB1 mutant melanoma patients, albeit not significantly." (PMID 36077603, 2022). "Of interest, CTNNB1 mutations occur in an unusual type of melanocytic nevus, termed “deep penetrating-nevus” (DPN) occurring in the skin, the conjunctiva and in extremely rare melanomas derived from such DPN." (PMID 34359736, 2021).